PPL (periplakin)
Diseases named in the same sentence as PPL in open-access papers (continued):
Sharing a sentence is not in itself a finding about the gene and the disease.
lymphoma (1 paper, 2016). A malignant (clonal) proliferation of B- lymphocytes or T- lymphocytes which involves the lymph nodes, bone marrow and/or extranodal sites. "Because the intrinsic pathway is the route described for PpL-induced apoptosis in normal B cells, we investigated if PpL was able to induce changes in the ΔΨm in murine lymphoma B cells." (PMID 27603942, 2016). "In the present study we show that protein L (PpL), secreted by Finegoldia magna, a B-cell Sag which interacts with κ+ bearing cells, induces the apoptosis of murine and human κ+ lymphoma B cells both in vitro and in vivo." (PMID 27603942, 2016). "Our results show that, as reported for normal κ+ B cells, PpL is able to alter the ΔΨm both in murine and human lymphoma cells, suggesting that the intrinsic pathway is involved in PpL-induced apoptosis." (PMID 27603942, 2016). "In the present study, we have investigated whether PpL -a B-cell Sag interacting with normal lymphocytes expressing the κ light chain in their BCR- is able to induce the apoptosis of κ+ malignant B cells using spontaneous murine lymphoma B cells and Daudi cells." (PMID 27603942, 2016). "Murine lymphoma cells were stained with CFSE and cultured in the presence of PpL." (PMID 27603942, 2016).
ovarian tumours (1 paper, 2024). "In conclusion, this study found significantly lower expression levels of the plakins, PLEC and PPL, in Type II compared to Type I ovarian tumours." (PMID 39682273, 2024). "However, the results described in our study are contrary to the results presented in a recent study where the mRNA and protein expression revealed significantly enhanced PPL expression in ovarian tumours compared to normal ovaries." (PMID 39682273, 2024). "In contrast, by immunohistochemistry analysis, we demonstrate that PPL staining is confined to the epithelial cells of benign tumours as well as other ovarian tumours without any obvious staining in the surrounding tissues." (PMID 39682273, 2024).
papilloma (1 paper, 2014). A benign epithelial neoplasm that projects above the surrounding epithelial surface and consists of villous or arborescent outgrowths of fibrovascular stroma. "We observed a downregulation of envoplakin, periplakin, and involucrin in WT papillomas and SCCs, leading us to speculate that the increased risk of SCC conversion in EPI−/− papillomas may be linked to the lack of two desmosomal proteins." (PMID 24843010, 2014).
psoriasis (1 paper, 2025). An autoimmune condition characterized by red, well-delineated plaques with silvery scales that are usually on the extensor surfaces and scalp. "However, unlike EPPK1, EVPL and PPL were not downregulated in lesional psoriasis, indicating a unique role of EPPK1 in psoriatic pathogenesis." (PMID 40746860, 2025).
pulmonary fibrosis (1 paper, 2021). Chronic progressive interstitial lung disorder characterized by the replacement of the lung tissue by connective tissue, leading to progressive dyspnea, respiratory failure, or right heart failure. "Periplakin and desmoplakin, two plakins linking the desmosomal plaque with intermediate filaments have also been implicated in lung fibrosis." (PMID 34093523, 2021). "Periplakin was initially identified as a potential contributor to pulmonary fibrosis due to the presence of anti-periplakin antibodies in the serum of 40% of IPF patients, and alterations in its alveolar expression." (PMID 34093523, 2021).
Ureteral obstruction (1 paper, 2013). Obstruction of the flow of urine through the ureter. "The expression of PPL and K19 in the renal cortex occurred synchronously, i.e., very low at the basal state and markedly increased after ureteral obstruction." (PMID 23849208, 2013).
urinary obstruction (1 paper, 2013). "In conclusion, PPL emerged as an intriguing unique molecule that dramatically accumulated at the cellular boundaries of hepatocytes and renal tubular epithelial cells in response to biliary and urinary obstruction." (PMID 23849208, 2013). "In addition, the robust accumulation of PPL found at the periphery of renal tubules following urinary obstruction suggests a similar role for this protein in the liver and kidney." (PMID 23849208, 2013).
tumor (20 papers, 2011 to 2026). "Genes such as ARHGEF28 and PPL were mutated in three of six ACC samples classified as other tumor sites." (PMID 30301885, 2018). "Previously we have shown that plakins (PPL, DSP, PLEC, EVPL) expressed in the ascites-derived tumour cells from patients with chemotherapy-treatment associated recurrence were significantly lower than plakins (PPL, DSP, EVPL, PLEC) in chemonaive ascites-derived tumour cells." (PMID 34001250, 2021). "There was a significant association between OS and PPL mRNA expression, when tumor residual size, grade, stage and age were included in the model, (P = 0.002, HR = 1.3, 95% CI 1.09–1.5), suggesting that PPL mRNA expression may be a potential independent prognostic biomarker for OV patients." (PMID 35612641, 2022). "This indicates that the expression level of PPL decreases significantly when the tumor load increases, such as in pathological stages III and IV." (PMID 40429589, 2025). "In a multivariable model adjusted for age, sex, H. pylori infection, histologic type, Lauren type, and tumor size, PPL/GAPDH (odds ratio 0.66 per 1 unit; p = 0.041) was the only statistically significant biomarker." (PMID 40429589, 2025). "Overall, in our samples, enhanced expression of PPL was noted in type I tumours compared to benign controls." (PMID 39682273, 2024). "In summary, the less aggressive and invasive phenotypes of borderline tumours, coherent with Type I tumours, retain significantly higher levels of PPL expression compared to aggressive Type II and grade 3 tumours." (PMID 39682273, 2024). "Subsequently, a similar difference in PPL expression was observed between benign and Type I and benign and stage 1 tumours." (PMID 39682273, 2024). "We demonstrate that there is a significant decrease in PPL expression between the Silverberg borderline and grade 3 tumours." (PMID 39682273, 2024). "PPL protein expression was similar, but potentially decreasing, between ovarian and omental tumour cells." (PMID 39682273, 2024). "This is consistent with our previous observation of high expression of PPL in epithelial cell-rich, low-grade/state/Type I tumours." (PMID 39682273, 2024). "According to public data, the PPL expression in OV tumor was demonstrated to be significantly higher than normal ovary in this study." (PMID 35612641, 2022). "Periplakin (PPL), which is over 7-fold higher in our cohort of F1 tumours compared to primary tumours, is also significantly overexpressed in the Badea gene expression set of PDAC tumours (n = 39) compared to normal pancreas tissue (n = 39)." (PMID 30404163, 2018). "Similar to desmoplakin and its tumor suppressor characteristics, the overexpression of periplakin suppressed the proliferation of colon cancer cells and reduced the expression of pro-cell cycle regulators." (PMID 29373494, 2018). "Other proteins of specific interest down regulated in CR tumor cells were members of plakin family such as PPL, EVPL and Plectin which function as ‘molecular bridges’ linking the intracellular cytoskeleton and cell-cell junctions." (PMID 27470985, 2016). "The methylation and expression levels strongly suggest that PPL expression was silenced by DNA hypermethylation in the PPL promoter in both the tumor samples and the tumor cell lines." (PMID 25583674, 2015). "In this study, we examined changes in cell growth, morphology, migration, and attachment activity following siRNA against PPL to investigate the involvement of PPL in tumor development." (PMID 21951621, 2011). "PPL knockdown appeared to decrease tumor cell growth together with G2/M phase accumulation in cells attached to a culture dish." (PMID 21951621, 2011). "In the case of PPL, a trend in increased PPL expression was noted with the stages and grades of tumours compared to normal ovaries, although it was only significant between stage 3 and normal ovaries, stage 3 and 4 tumours, and grades 2 and 3 tumours." (PMID 39682273, 2024).
tumor (continued). "The change in PPL expression was significant between the Type I (low grade) and Type II (high grade) tumours, which may be consistent with the dissimilar genetic profiles suggested for these classifications." (PMID 39682273, 2024). "Similarly, tumours classed as surgical stage 1 have significantly higher PPL expression than those in higher FIGO stages of tumour dissemination, with a similar trend observed in the expression of PLEC." (PMID 39682273, 2024). "PPL might act as a tumor suppressor and a new biomarker or potential therapeutic target in colon cancer." (PMID 35612641, 2022). "The expression of PPL was tested in the 42 tumor samples and 10 normal ovaries, respectively." (PMID 35612641, 2022). "A potential correlation between immune cells and PPL expression implied that PPL might own the potential of crucial function in tumor immune microenvironment." (PMID 35612641, 2022). "Using immunohistochemistry, PPL expression was observed at cell–cell boundaries of normal oesophageal epithelium and dysplastic lesions, whereas it relocated to the cytoplasm in early cancers and was scarcely expressed in advanced tumours." (PMID 34001250, 2021). "The authors found that PPL knockdown decreased tumor cell growth, adhesion to ECM." (PMID 25583674, 2015). "In TNBC cell lines, reduced expression of PPL by siRNA, resulted in reduced cell migration and invasion, but had increased cell growth in soft agar, suggesting that reduced expression of PPL in brain metastasis may be important for the growth of tumours in TNBC patients." (PMID 34001250, 2021). "In this study we demonstrate that the expression of PPL and EVPL is lower in the benign samples than in the Type I tumours." (PMID 39682273, 2024). "The most interesting results are the significant decrease in PPL and PLEC expression in Type II compared to Type I tumours." (PMID 39682273, 2024). "Most interestingly, periplakin (PPL) had the highest change in expression levels, with a 7.85-fold increase in PDX F1 compared to primary PDAC tumours." (PMID 30404163, 2018). "Collectively, PPL suppression reduced cell motility, and ECM invasion, all of which generate tumor progression by increasing infiltrating activity in pharyngeal squamous cancer cells." (PMID 21951621, 2011). "Additionally, PPL and TGM1 levels were correlated with N status in both tumor and margin samples, respectively." (PMID 41695373, 2026). "Among the known salivary extracellular RNA biomarkers examined in this study, the pre-operative expression levels of PPL, SEMA4B, and miR140-5p were significantly correlated with high tumor burden (which we defined as stages III and IV), along with age and sex." (PMID 40429589, 2025). "Their trend of expression showed most of them to be upregulated in the tumor samples, regardless of the disease stage, while only PPL, ALDH1A1, GSTA1, TJP3 and CRYAB were downregulated in HNSCC." (PMID 37686696, 2023). "Univariate independent prognostic analysis showed that age (p < 0.001), tumor grade (p < 0.001), PCDH18 (p < 0.05), PPL (p < 0.01), DEPP1 (p < 0.01), VASN (p < 0.001), KCNE4 (p < 0.001), MYBPH (p < 0.001), C5AR2 (p < 0.01), and MARCH4 (p < 0.01) gene expression levels were significantly different." (PMID 39281062, 2022). "This may indicate a role for PPL in PDAC tumour progression through Akt, and its increased expression in the PDX F1 tumour cohort suggests it may be driving tumour growth by increasing proliferation." (PMID 30404163, 2018). "To test whether this influences tumour formation, we chemically induced tumours in EPI−/− mice, which lack three barrier proteins—Envoplakin, Periplakin, and Involucrin." (PMID 24843010, 2014).
cancer (14 papers, 2011 to 2025). A tumor composed of atypical neoplastic, often pleomorphic cells that invade other tissues. "Little is known, however, about the molecular mechanism underlying the regulation of PPL expression and the contribution of PPL loss to the malignant property of the cancer is unclear." (PMID 25583674, 2015). "PPL expression levels are associated with cancer progression 5 and nodal metastasis." (PMID 25583674, 2015). "The previous observations suggested that the effect of PPL expression on the function of cancer cells differ greatly, which was regulated by autocrine or paracrine factors that modulates cell cycle properties." (PMID 35612641, 2022). "We previously showed that periplakin expression was significantly correlated with the aggressive pathology and cancer-specific survival in patients with BC." (PMID 34680299, 2021). "In vitro experiments on cancer cell lines have shown that, the expression of PPL have varied results on cellular functions." (PMID 34001250, 2021). "PPL also showed the highest gene expression in PDAC compared to 11 other cancer types in the Ramaswamy 2001 multi-cancer gene expression set." (PMID 30404163, 2018). "More recently, envoplakin and periplakin, functioning as epidermal barrier components, have also attracted attention in cancer development." (PMID 29587367, 2018). "On the other hand, proteome analysis of human esophageal cancers demonstrated that PPL was significantly downregulated in cancer tissues and was scarcely expressed in advanced-stage cancers." (PMID 25583674, 2015). "In accordance with those results, the PPL mRNA levels determined by RT-PCR were significantly decreased in the cancer tissues compared with those in the normal mucosa." (PMID 25583674, 2015). "If PPL expression relates to cellular migration, movement or invasion, PPL expression should be different among normal, atypical epithelium and cancers." (PMID 21951621, 2011). "Immunohistochemical staining has also revealed that PPL changes its cellular localization as well as its expression levels with cancer progression." (PMID 21951621, 2011). "PPL also plays a role as a localization signal in oncogenic serine/threonine protein kinase Akt/protein kinase B (PKB)-mediated signaling in human cancer cell lines." (PMID 21951621, 2011). "In human cancer cells, PPL could also function as a localization signal in the oncogenic threonine/serine protein kinase Akt/protein kinase B (PKB)-mediated signaling." (PMID 35612641, 2022). "PPL was reported to be a potential biomarker candidate for several types of cancers." (PMID 35612641, 2022). "PPL has been extensively studied as a binding partner of Akt, which is well-established for its role in cell proliferation, migration, apoptosis, and various cancers." (PMID 30404163, 2018). "They reported that an overexpression of periplakin reduced cancer cell migration and invasion, induced a G1/G0 cell cycle arrest, and inhibited colon cancer cell proliferation by suppressing the activation of ERK1/2 and the expression of proliferating cell nuclear antigen (PCNA)." (PMID 29587367, 2018). "Finally, we examined changes in the expression of phospholipid signaling proteins that regulate cell migration because PPL has been reported to play a role as a scaffold in Akt/PKB signaling in human cancer cell lines." (PMID 21951621, 2011). "Under this hypothesis, we immunohistochemically examined PPL expression in excised human normal, atypical epithelium and in cancer of the pharyngeal mucosa." (PMID 21951621, 2011). "From above all, the possible roles of PPL might be different among various cancer types." (PMID 35612641, 2022). "Furthermore, the inconsistent prognosis implications of PPL expression in pan-cancer were observed." (PMID 35612641, 2022). "HPV+ SiHa cancer cells expressed high levels of CEBPD, SLPI, and PPL mRNA relative to HFKs and HPV-C33A cancer cells." (PMID 34944802, 2021).
cancer (continued). "We show that proteins such as PPL that interacts with signalling molecules could confer resistance to kinase inhibitors and affords an opportunity to investigate PPL as a biomarker for cancer therapeutics that directly or indirectly inhibits AKT phosphorylation." (PMID 30787334, 2019). "Downexpressions of EVPL and PPL can also be found in the majority of datasets (26 for EVPL and 51 for PPL) across the cancer types." (PMID 29587367, 2018). "Among the cancer-specific hypermethylated genes, SCGB3A1 and PPL were already reported to have hypermethylation at its promoter, leading to reduced expression in ESCC." (PMID 29137437, 2017). "Note that in both the non-keratinized (asterisk) and keratinized cancer areas (arrows), PPL expression was scarce." (PMID 21951621, 2011). "However, EMT in cancer involves downregulation of the expression of desmosomal, adherens/tight junction and cytolinker proteins such as E-cadherin, occludens, claudins, EpCAM, α6β4 integrin, different cytokeratins, DSP, PPL." (PMID 34001250, 2021). "There were no researches about the roles of FUT7, PADI1, PPL, and ARHGAP40 in LSCC, but the roles of these genes or the related genes in other cancers were reported." (PMID 34131588, 2021).
benign tumours (2 papers, 2014 to 2024). "Thus combined deletion of envoplakin, periplakin, and involucrin decreased epidermal susceptibility to chemically induced benign tumours." (PMID 24843010, 2014). "In this study, we investigated the expression of plakins (PPL, EVPL, PLEC) in different stages, grades, and Types of serous ovarian tumours compared to benign tumours of the same origin." (PMID 39682273, 2024).
renal disorders (1 paper, 2013). "Time- and context-dependent expression of PPL in various mouse models of hepatic and renal disorders were examined by immunohistochemistry, western blotting, and quantitative real-time polymerase chain reactions." (PMID 23849208, 2013).
PPL also shares sentences with these, for which no sentence is quoted: breast carcinoma (2 papers); melanoma (2); adenoid cystic carcinoma (1); adrenocortical carcinoma (1); bacterial infection (1); Burkitt ́s lymphoma (1); cervical cancer (1); COVID-19 (1); digestive tumors (1); eosinophilic esophagitis (1); heart disease (1); infection (1); infertile (1); lung adenocarcinoma (1); metastatic cancer (1); myeloma (1); Obesity (1); pancreatic ductal adenocarcinoma (1); prostate carcinoma (1); sarcoma (1); steatosis (1); stomach adenocarcinoma (1); thyroid cancer (1); urothelial carcinoma (1); uterine corpus endometrial carcinoma (1); vitiligo (1).